DKK2 (dickkopf Wnt signaling pathway inhibitor 2)
Description:
Antagonizes canonical Wnt signaling by inhibiting LRP5/6 interaction with Wnt and by forming a ternary complex with the transmembrane protein KREMEN that promotes internalization of LRP5/6. DKKs play an important role in vertebrate development, where they locally inhibit Wnt regulated processes such as antero-posterior axial patterning, limb development, somitogenesis and eye formation. In the adult, Dkks are implicated in bone formation and bone disease, cancer and Alzheimer disease (By similarity).
Synonyms: Dkk-2
Tractability: Antibody: UniProt places it where antibodies can reach, with medium confidence; UniProt predicts a signal peptide or a membrane-spanning region; its Gene Ontology location is reachable by antibodies, with medium confidence.
Gene: Protein-coding gene on chromosome 4 (106,921,802 to 107,283,806, reverse strand). Ensembl gene ENSG00000155011.
Subcellular location: Secreted
Subcellular location (Human Protein Atlas): Golgi apparatus; Predicted to be secreted
Pathways (Reactome):
Signal Transduction: Negative regulation of TCF-dependent signaling by WNT ligand antagonists; TCF dependent signaling in response to WNT
Chromatin organization: CHD6, CHD7, CHD8, CHD9 subfamily
Disease: Signaling by LRP5 mutants
Gene Ontology:
Molecular function: protein binding; co-receptor binding; receptor antagonist activity
Biological process: negative regulation of canonical Wnt signaling pathway; positive regulation of canonical Wnt signaling pathway; negative regulation of Wnt signaling pathway
Cellular component: extracellular region; Golgi apparatus
Genetic constraint (gnomAD): Loss-of-function variants: 11 observed, 29.34 expected, observed/expected ratio (o/e) 0.37, 90% interval 0.23 to 0.62. The upper end of that interval is the gene's LOEUF score, 0.62, which puts it in group 2 of 6, group 1 being the genes least tolerant of losing a copy. Missense variants: 326 observed, 354.51 expected, observed/expected ratio (o/e) 0.92, 90% interval 0.84 to 1.01. Synonymous variants: 135 observed, 135.21 expected, observed/expected ratio (o/e) 1, 90% interval 0.87 to 1.15.
Homologues: Orthologues: chimpanzee DKK2 (98% identical), macaque DKK2 (98% identical), pig DKK2 (97% identical), dog DKK2 (96% identical), rat Dkk2 (96% identical), mouse Dkk2 (95% identical), rabbit DKK2 (95% identical), guinea pig DKK2 (95% identical).
Diseases named in the same sentence as DKK2 in open-access papers:
DKK2 is named in the same sentence as 86 diseases in open-access papers, as found by Europe PMC text mining. Sharing a sentence is not in itself a finding about the gene and the disease. The quoted sentences say what the papers report.
colorectal cancer (15 papers, 2016 to 2026). A primary or metastatic malignant neoplasm that affects the colon or rectum. "The loss of LYZ+ cells by Dkk2 knockout rescued mice from the liver metastasis of colorectal cancer induced by cancer organoid transplantation." (PMID 38659853, 2024). "Recently, we have identified DKK2 as a novel tumor immune-suppressive protein in the microenvironment in colorectal cancer carrying APC mutation." (PMID 31372243, 2019). "Our recent studies also showed that DKK2 promotes tumor progression by suppressing cytotoxic immune cell activation in colorectal carcinoma with APC mutations." (PMID 31372243, 2019). "In our recent study, we uncovered a function of DKK2 in promoting tumor progression by suppressing cytotoxic immune cell activation in colorectal carcinoma with APC mutations." (PMID 31372243, 2019). "Our previous study has proved that anti-DKK2 antibody 5F8 suppressed the growth of colorectal carcinoma with APC mutations, illustrating a new target agent of APC-mutated tumors." (PMID 31372243, 2019). "The previous literature has reported that the methylation of DKK2 plays a significant role in the development of colorectal cancer." (PMID 40340623, 2025). "This extends our knowledge of colorectal cancer progression that DKK2 is required for the generation of LYZ+ cells forming cancer stem cell niches." (PMID 38659853, 2024). "In sum, our findings suggest that a Wnt ligand, DKK2 is an upstream regulator of SOX9 expression for enhanced stem cell activity via the formation of LYZ+ cells with Paneth cell characteristics in colorectal cancers." (PMID 38659853, 2024). "The Dickkopf protein DKK2 has also been reported to be expressed in colorectal cancer stem cells and to modulate cancer progression." (PMID 35296660, 2022). "With this study, we found that there is an enhanced cytotoxic T cell response after anti-DKK2 antibody treatment, which is dependent on DKK2 expression via in vitro human colorectal cancer tissue culture system." (PMID 32559853, 2020). "In this study, we revealed that enhanced cytotoxic T cell response of anti-DKK2 antibody 5F8 treatment is dependent on DKK2 expression in human colorectal cancer samples." (PMID 32559853, 2020). "Xiao and his colleagues found that the high expression of DKK2 in colorectal cancers (CRC) results in impaired tumor immune evasion." (PMID 31583260, 2019). "Another tumor-secreted protein, the Dickkopf-related protein 2 (DKK2), was shown to be overexpressed in human colorectal cancers and melanomas, and to promote tumor progression by suppressing the activation of both CD8 T and NK cells." (PMID 31766350, 2019). "Thanks to the immunity-related pathway suggested by GSEA and Xiao and his colleagues' work that a high expression of DKK2 in colorectal cancers (CRC) results in impaired tumor immune evasion." (PMID 31583260, 2019). "We then developed an anti-DKK2 antibody for the immunotherapeutic treatment of colorectal cancer with APC mutaions." (PMID 31372243, 2019). "SFRP1, SFRP2, and DKK2 were appropriate markers to differentiate colorectal cancer cells from normal crypt cells." (PMID 28533824, 2017). "Based on these observations, we queried whether DKK2 is required for metastasis of colorectal cancer." (PMID 38659853, 2024). "In addition, the 5F8 antibody was able to specifically inhibit DKK-2 in an in vivo model of colorectal cancer." (PMID 34451907, 2021).
colorectal cancer (continued). "Interestingly, DKK-2 has also been involved in the enhancement of stemness in colorectal cancer, via the activation of the tyrosine-kinase Src and degradation of HNF4α1 protein." (PMID 34451907, 2021). "To verify whether DKK2 blockade activates infiltrating CD8+ T cells in human colorectal cancers, we collected 16 human colorectal tumor samples." (PMID 32559853, 2020). "Overexpression of DKK2 has been reported in Ewing sarcoma and colorectal cancer." (PMID 31583260, 2019). "In addition, our results suggest that SFRP1, SFRP2, and DKK2 markers can differentiate colorectal cancer cells from normal crypt cells." (PMID 28533824, 2017). "DKK2 protein was seen overexpressed in Ewing sarcoma, colorectal cancer and reduce in melanoma." (PMID 27457487, 2016). "In vitro, these bacteria were co-cultured with colorectal cancer cells and KDM6B-overexpressing colorectal cancer cells to test their effect on KDM6B inhibition and DKK2 expression." (PMID 40340623, 2025). "Characterization of DKK2-induced LYZ+ cancer cells will provide better understanding of the biology of cancer stem cell niches, particularly in liver metastases of colorectal cancer." (PMID 38659853, 2024). "Collectively, DKK2 is required for the generation of LYZ+ cells to form the cancer stem cell niche, a prerequisite for the outgrowth of metastasized colorectal cancer cells." (PMID 38659853, 2024). "As we showed previously and in this study, DKK2 antibody suppresses tumor growth in both APC mutant NSCLC and APC mutant colorectal cancer." (PMID 31372243, 2019). "Anti-DKK2 treatment induced significant increases in GZMB and CD69 over control IgG treatment in the DKK2high, but not DKK2low sample group, suggesting that DKK2 blockade activates infiltrating CD8+ T cells in human colorectal cancers that express high levels of DKK2." (PMID 32559853, 2020). "However, increased expression and secretion of Wnt antagonist Dickkopf-related protein 2 (DKK2) by tumor cells inhibited T-cell function and promoted tumor progression in colorectal cancer, independent of β-catenin." (PMID 31261718, 2019).
melanoma (11 papers, 2009 to 2026). A malignant, usually aggressive tumor composed of atypical, neoplastic melanocytes. "Its association with tumor immune evasion in some subsets of melanoma and colorectal tumors has also been reported, where DKK-2 depletion activates natural killer (NK) cells and CD8+ T cells and inhibits tumor progression." (PMID 37761972, 2023). "Cluster c5 highly expressed Dkk2, a putative Wnt signaling inhibitor down-regulated in melanoma and Cdh13 (T-cadherin), an adhesion molecule that influences the migration and invasion of melanoma cells and that functions as a pro-apoptotic tumor suppressor." (PMID 39457009, 2024). "Some telomere length maintenance genes (TERC, OBFC1) regulate both nevus count and melanoma risk, while the majority regulate melanoma risk only (such as TERT, DKK2, NAF1)." (PMID 36834954, 2023). "Collectively, these results suggest that the effects of DKK1 and DKK2 on B16F10 melanoma growth are mainly exerted through regulating angiogenesis with no direct action on tumor cell proliferation." (PMID 24091497, 2014). "Treatment of B16F10 melanoma-bearing mice with adenovirus expressing DKK1 significantly reduced tumor growth but DKK2 increased growth compared with controls." (PMID 24091497, 2014). "To study the effect of DKK1 and DKK2 on tumor angiogenesis and proliferation, we injected either adenoviral-mDKK1 (Ad-DKK1) or -mDKK2 (Ad-DKK2) constructs into B16F10 melanomas that had been established in syngeneic C57BL/6 mice." (PMID 24091497, 2014). "To assess this possibility, we evaluated DKK1 and DKK2 effects on B16F10 melanoma cellular function." (PMID 24091497, 2014). "In the case of DKK2, its suppression in tumors such as malignant melanoma and gastrointestinal tumors has been reported, but the elevated levels in cancer have not." (PMID 19247449, 2009). "On the contrary, melanoma growth was accelerated in DKK2 Tg mice versus wild-type controls (3,844 ± 252 vs. 2,874 ± 140 mm3, respectively; p < 0.001) and mouse survival was significantly reduced in DKK2 Tg mice (p < 0.001)." (PMID 24091497, 2014). "DKK1 and DKK2 were undetectable in B16F10 melanoma cells, whereas DKK3 and DKK4 were expressed." (PMID 24091497, 2014). "DKK1, DKK2 and DKK3 downregulation has been observed in melanoma cell lines and tissue samples, however, in contrast to other cancer types promoter hypermethylation is responsible only for downregulation of DKK2." (PMID 32659938, 2020). "We injected B16F10 melanoma cells into DKK1 Tg and DKK2 Tg mice, and their wild-type littermates, and evaluated tumor growth and angiogenesis." (PMID 24091497, 2014). "In the present study, we investigated the effects of DKK1 and DKK2 in tumor growth and angiogenesis in a murine model of B16F10 melanoma." (PMID 24091497, 2014). "This study examined the effects of DKK1 and DKK2, known Wnt antagonists, on B16F10 melanoma tumor proliferation and angiogenesis by using viral-mediated tumor transfectants and transgenic mice." (PMID 24091497, 2014). "We constructed stable DKK1 and DKK2 B16F10 melanoma cell lines by transfection with lenti-viral vectors (Lenti-DKK1 and Lenti-DKK2)." (PMID 24091497, 2014). "In melanoma and gastrointestinal cancers, DKK2 expression is markedly decreased; however, the details of Dkk2 function were not well investigated." (PMID 25826080, 2016). "Unlike Ad-DKK1, Ad-DKK2 infection increased B16F10 melanoma vessel density to levels 171 % of Ad-Mock controls." (PMID 24091497, 2014). "Neither DKK1 nor DKK2 stable melanoma cell line proliferation was significantly different compared to the Lenti-GFP cell line." (PMID 24091497, 2014). "However, we found that both DKK1 and DKK2 did not modulate tumor cell proliferation in stably-transfected melanoma cells." (PMID 24091497, 2014). "Neither DKK1 nor DKK2 affect B16F10 melanoma cell proliferation and survival." (PMID 24091497, 2014).
breast cancer (10 papers, 2013 to 2025). A primary or metastatic malignant neoplasm involving the breast. "Thus, defining the underlying mechanisms of DKK2 in breast cancer development may support the idea that DKK2 may be a potential treatment target and marker in breast carcinoma." (PMID 28467796, 2017). "Our findings indicated that DKK2 inhibited β-catenin activity, thus inhibiting Wnt/β-catenin signaling in mammary cancer." (PMID 28467796, 2017). "DKK2 promoter methylation was detected in 77.8% of cell lines and 86.7% of breast tumors; while rarely detected in normal breast tissues (19%), indicating common DKK2 methylation in breast cancer." (PMID 28467796, 2017). "Recently, silencing of DKK2 was reported to be a valuable biomarker for multiple malignancies, but its roles in breast cancer are still unclear." (PMID 28467796, 2017). "DKK2 methylation was detected in 85/98 (86.7%) breast tumors, 4/21 (19%) in normal tissues, indicating that DKK2 methylation was a common in breast cancer." (PMID 28467796, 2017). "Alternatively, the downregulation of DKK2 was related to clinicopathological subtypes of breast cancer according to data from Oncomine database (Oncomine, Compendia Bioscience, Ann Arbor, MI) (p < 0.00001)." (PMID 28467796, 2017). "Here we investigated the expression and significance of DKK2 in mammary cancer, as well as its functions in vivo and in vitro." (PMID 28467796, 2017). "Our findings demonstrate that DKK2 inhibited breast cancer growth through downregulating activated β-catenin levels." (PMID 28467796, 2017). "Altogether, these data indicated that the reduced DKK2 expression was a solid fact in breast carcinoma." (PMID 28467796, 2017). "All in all, our data demonstrated that DKK2 can inhibit breast carcinoma growth via suppressing Wnt/β-catenin signaling." (PMID 28467796, 2017). "All these results indicated that DKK2 methylation is a potential marker for breast carcinoma early detection." (PMID 28467796, 2017). "We also observed frequent methylation of DKK2 in breast cancer, which was reported in gastrointestinal and renal cancers." (PMID 23890219, 2013). "Thus, DKK2 silencing or downregulation was the result of promoter CpG methylation in breast cancer cells." (PMID 28467796, 2017). "One possible explanation for this might be that DKK2 may inhibit or induce angiogenesis through directly affect WNT signaling in breast cancer, depending on different Wnt signaling acitivity in different microenvironment." (PMID 28467796, 2017). "The tumor-specific promoter methylation of DKK2 could be a potential marker for the early assessment of mammary cancer." (PMID 28467796, 2017). "Furthermore, we showed that DKK2 mRNA level was significantly lower in breast cancer tissues than that in paired surgical-margins by qRT-PCR (*p < 0.05)." (PMID 28467796, 2017). "However, DKK2 methylation was not statistically associated with age, tumor size, clinical stage, metastasis, or ER, PR, HER2 status of breast carcinoma patients through analyzing the DKK2 promoter methylation and patient clinicopathological characters." (PMID 28467796, 2017). "Therefore, GAS5 activates the Wnt/β-catenin signaling pathway via the GAS5/miR-221-3p/DKK2 axis and may be used to enhance the sensitivity of breast cancer patients to ADR treatment." (PMID 34202777, 2021). "Furthermore, the DKK2 promoter methylation status could be a potential tumor marker for early found of mammary carcinoma, or even offer a new therapeutic method for breast carcinoma." (PMID 28467796, 2017). "In breast cancer, GAS5 participates in the activation of proteins that include PTEN, PDCD4, DKK2, FOXO1, and SUFU through a ceRNA mechanism mediated by various miRNAs, including miR-21, miR-222, miR-221-3p, miR-196a-5p, and miR-378a-5p." (PMID 34202777, 2021).
breast cancer (continued). "In breast cancer, miR-221 is the target of GAS5, and GAS5 regulates DKK2 expression by competitively binding miR-221-3p, inhibiting the activation of Wnt / β-Catenin pathway, enhancing the anti-tumor effect of adriamycin." (PMID 34022918, 2021). "In contrast, while overexpressed GAS5 can strengthen ADR sensitivity in vivo and in vitro, GAS5 acted as a sponge to miR-221-3p and subsequently drove the expression of dickkopf 2 (DKK2), which ultimately inactivated the Wnt/β-catenin pathway to weaken ADR resistance in breast cancer cells." (PMID 36613528, 2022). "Furthermore, 98 primary breast carcinoma tissues and 21 normal mammary tissues were analyzed by MSP to investigate DKK2 methylation in breast tumors." (PMID 28467796, 2017). "In cardiomyocytes, DKK2 was also proven by our results to be the negative modulator of Wnt/β‐catenin signaling, and functioned as the intermediary in miR-221/222 regulating Wnt/β‐catenin, which were revealed in previous work of breast cancer." (PMID 35836108, 2022). "DKK2 may play a key role in metastasis promotion and breast cancer development, but its role in ovarian tissue has not been defined." (PMID 35011815, 2021). "A recent study that reported a role of DKK-2 in chemoresistance in breast cancer it is also noteworthy, with a description of the long non-coding RNA GAS5 as an endogenous “sponge” competing with miRNA-221-3p to regulate its target DKK-2, which in turn, inhibits the activation of Wnt pathway." (PMID 34451907, 2021). "Again it indicated that DKK2 may inhibit both EMT and stemness of breast carcinoma cells." (PMID 28467796, 2017). "MSP analysis revealed that both DKK2 (data not shown) and DKK3 methylation were frequently detected in breast cancer lines." (PMID 23890219, 2013).